MKLN1-AS (MKLN1 antisense RNA)
Synonyms: MKLN1-AS2
Gene: Long non-coding RNA gene on chromosome 7 (131,309,469 to 131,328,312, reverse strand). Ensembl gene ENSG00000236753.
Diseases named in the same sentence as MKLN1-AS in open-access papers:
MKLN1-AS is named in the same sentence as 1 disease in open-access papers, as found by Europe PMC text mining. Sharing a sentence is not in itself a finding about the gene and the disease.
MKLN1-AS shares sentences with these, for which no sentence is quoted: hepatoma (1 paper).